ENG (endoglin)
Diseases named in the same sentence as ENG in open-access papers (continued):
Sharing a sentence is not in itself a finding about the gene and the disease.
Cirrhosis (10 papers, 2007 to 2026). A chronic disorder of the liver in which liver tissue becomes scarred and is partially replaced by regenerative nodules and fibrotic tissue resulting in loss of liver function. "Reduced levels of circulating BMP10 and BMP9, along with elevated levels of endoglin, have been associated with disease severity, decompensation, and pulmonary vascular syndromes in patients with cirrhosis." (PMID 39199400, 2024). "Conversely, endoglin MVD scores were significantly higher in cirrhosis than in HCC and DN, and were higher in DN compared with HCC." (PMID 24507660, 2014). "Patients with HCV-related cirrhosis also demonstrated higher levels of serum endoglin compared to those with fibrosis but without cirrhosis." (PMID 39199400, 2024). "Endoglin was present in both the neo-vessels in tumor tissues and the hepatic sinus endothelium in the nontumor tissue in those with cirrhosis." (PMID 33809908, 2021). "The large spectrum of endoglin effects in the liver is cell-type specific, depends on aetiology (higher expression in HCV infection), and is HCC stage-specific (higher expression in HCC with cirrhosis)." (PMID 30563158, 2018). "Therefore, before potential therapeutic antiangiogenic targeting with CD105 in HCC and cirrhosis patients, further studies investigating the function of endoglin in cirrhotic livers are required." (PMID 24507660, 2014). "Serum TIMP-4 and Endoglin showed highest values in HCV patients with liver cirrhosis compared to those with fibrosis but without cirrhosis." (PMID 23516586, 2013). "We found them to be upregulated in cirrhosis represented by the upregulation of PGDFRB, TGFB1 (TGF‐β1), TGFB1I1 (TGF‐β1 induced transcript 1 protein), TGFBI (TGF‐β induced protein ig‐h3), LTBP1, LTBP2, LTBP4, and ENG (transmembrane accessory receptor for TGF‐beta signaling)." (PMID 35579278, 2022).
COVID-19 (10 papers, 2021 to 2024). A disease caused by infection with severe acute respiratory syndrome coronavirus 2. "Of the 107 patients with ascertained COVID-19, 50 had a known genetic mutation in ENG (18/50), ACVRL1 (31/50) or SMAD4 (1/50)." (PMID 37140873, 2023). "In the 9 ascertained COVID-19 patients, the HHT-causing mutation was located in the ENG gene (HHT1) and in the ALK1/ACVRL1 gene (HHT2) in 3 and 6 patients, respectively, thus resulting in an overlapping distribution with the COVID-19-free patients." (PMID 34496900, 2021). "Additionally, 13 of 55 angiogenic proteins including TIMP-1, uPA, VEGF, MMP-8/9, CXCL4/16, Endoglin, Angiogenin or Angiopoietin-2 were uniquely downregulated in 3-months post-COVID-19 patients without PE compared to those who suffered a PE." (PMID 38324145, 2024).
gastric cancer (10 papers, 2016 to 2026). A primary or metastatic malignant neoplasm involving the stomach. "By analyzing the co-expression correlation between CPT1A, IL-8, CXCL5, STC1 and CD44 in stomach cancer tissues through TCGA database, we found that these genes except CXCL5 were positively correlated with CD44 and were positively associated with at least one MSC markers (ENG, THY1, NT5E)." (PMID 37158903, 2023). "A subpopulation of MSCs expressing specific marker genes such as THY1, SPARC, ENG, PRRX1, VCAM1, and MCAM has been identified in primary lesions, ovarian metastases, and peritoneal metastases of gastric cancer." (PMID 40676710, 2025). "For example, gastric cancer cells can silence the endoglin expression in PMCs via the TGF-β pathway, thereby inducing the senescence of PMCs and thus enhancing the adhesion and invasion of gastric cancer cells." (PMID 35740521, 2022). "Between the TGF-β family co-receptors (ENG and TGFBR3) implicated in cancer progression and inhibin function, ENG was more expressed, particularly in lung adenocarcinoma and gastric cancers, corresponding with ENG being a strong negative predictor of survival." (PMID 33819300, 2021).
Hypercholesterolemia (9 papers, 2015 to 2022). An increased concentration of cholesterol in the blood. "Hypercholesterolemia alters endoglin expression and signalling, causing endothelial or vascular dysfunction before the initiation of atherosclerotic lesions." (PMID 32523017, 2020). "It was demonstrated that soluble endoglin levels are higher in patients with familial hypercholesterolemia when compared to healthy controls." (PMID 33640001, 2021). "Membrane endoglin (Eng) expression is shown to participate in fibrosis, and plasma concentrations of soluble endoglin (sEng) are increased in patients with hypercholesterolemia and type 2 diabetes mellitus." (PMID 33261044, 2020). "Moreover, hypercholesterolemia, coronary heart disease, DM and HT contribute to increase serum endoglin levels." (PMID 32523017, 2020). "Moreover, soluble endoglin levels were reduced after a series of two aphereses, suggesting that soluble endoglin serves as an indicator of a beneficial and sufficient procedure in patients with familial hypercholesterolemia." (PMID 33640001, 2021).
liver cirrhosis (9 papers, 2006 to 2024). "This study demonstrated a close relationship between endoglin and liver cirrhosis, in contrast to CD34 antibody, which is a good endothelial marker of hepatic carcinogenesis." (PMID 24507660, 2014). "Similar to our observations for TIMP-4, Endoglin serum levels were highest in HCV patients with complete liver cirrhosis, suggesting a close relation to hepatic staging." (PMID 23516586, 2013). "In addition, an Egyptians study on patients with cirrhosis of the liver found that elevated endoglin and TGF-β mRNA promote hepatocarcinogenesis and increase the risk of HCC." (PMID 33809908, 2021). "In addition, patients with chronic HCV infection and liver cirrhosis were found to have high intrahepatic and circulating endoglin levels." (PMID 31749832, 2019). "Observations of higher endoglin expression (mRNA, protein) in ECs present in NT tissue (including liver cirrhosis), compared to a tumour, and positive correlations of such expression with clinical advancement or prognosis of HCC, can be found in the literature." (PMID 30563158, 2018). "Therefore, it is suggested that endoglin is not a suitable target for anti-angiogenesis treatment in those with liver cirrhosis." (PMID 33809908, 2021).
lymph node metastasis (9 papers, 2003 to 2022). "On multivariable logistic regression modeling, elevated preoperative plasma levels of endoglin were significantly associated with an increased risk of lymph node metastasis, ≥pT3 disease, and any NOCD (all p < 0.001)." (PMID 34587660, 2022). "According to our results, preoperative plasma endoglin level was a strong predictor of lymph node metastasis, ≥pT3 disease, and any NOCD in patients treated with RC for nonmetastatic UCB." (PMID 34587660, 2022). "According to DCA, in our study, the addition of endoglin improved the clinical net benefit of the standard model for the prediction of lymph node metastasis; indeed, 67.8% of patients would benefit from the novel model featuring endoglin." (PMID 34587660, 2022). "The addition of endoglin to established preoperative variables improved the ability to predict lymph node metastasis by a statistically and clinically significant margin, while for ≥pT3 disease and NOCD prediction, the margin was minimal." (PMID 34587660, 2022). "Median plasma levels of endoglin were significantly higher among patients with adverse pathologic features such as lymphovascular invasion (p < 0.001), lymph node metastasis (p < 0.001), contaminant CIS (p < 0.01), and advanced pathologic tumor stage (p < 0.001)." (PMID 34587660, 2022). "Higher preoperative endoglin level was independently associated with an increased risk for lymph node metastasis, ≥pT3 disease, and nonorgan confined disease (NOCD; all p < 0.001)." (PMID 34587660, 2022).
Myocardial fibrosis (9 papers, 2013 to 2022). "Treatment with atorvastatin can also decrease myocardial fibrosis through attenuating miR-208a and endoglin expression in experimental AMI." (PMID 34279451, 2021). "One of them—rno-miR-344a-2—was previously associated with aging and regulation of a-SMA and the other—rno-miR-208a-3p—mediates the myocardial endoglin expression that led to increased myocardial fibrosis." (PMID 34869342, 2021). "Conversely, it has been demonstrated that treatment with valsartan can decrease myocardial fibrosis through attenuating miR-208a and endoglin expression." (PMID 34279451, 2021). "Endoglin upregulation has been reported in myocardial fibrosis, in the skin of patients with scleroderma, and in intestinal fibroblasts in patients with Crohn’s Disease." (PMID 33081058, 2020). "In conclusion, epigallocatechin‐3‐O‐gallate (EGCG) attenuated the endoglin expression and myocardial fibrosis by anti‐inflammatory effect in vitro and in vivo, the novel suppressive effect was mediated through JNK/AP‐1 pathway." (PMID 27306149, 2016). "Studies have shown that miR-208a functions via upregulation of endoglin to increase myocardial fibrosis, and its silencing downregulates endoglin and reduces type 1 collagen synthesis." (PMID 26688617, 2015). "In this study, we further confirm that atorvastatin can reduce myocardial fibrosis through reducing endoglin expression in volume overloading heart." (PMID 24392114, 2014). "Treatment with atorvastatin can attenuate the myocardial fibrosis induced by volume overload through inhibition of endoglin expression." (PMID 24392114, 2014). "Treatment with atorvastatin can attenuate myocardial fibrosis induced by volume overload through inhibition of endoglin expression." (PMID 24392114, 2014). "In conclusion, we showed that EGCG attenuated endoglin expression and myocardial fibrosis in vitro and in vivo, and that the novel suppressive effect was mediated through endoglin/JNK/AP‐1 pathway, which suggested the strong implications in controlling human cardiovascular diseases." (PMID 27306149, 2016). "Therefore, the aim of this study was to elucidate the effect of EGCG on the myocardial fibrosis model and cultured Ang II‐induced CFs; in addition, the study investigated the myocardial fibrosis and endoglin molecular modulation." (PMID 27306149, 2016). "The increased endoglin to induce myocardial fibrosis induced by AV shunt was mediated by mir-208a." (PMID 24392114, 2014).
sarcoma (9 papers, 2012 to 2024). A usually aggressive malignant neoplasm of the soft tissue or bone. "In addition, endoglin expression on RCC cells and certain sarcoma subtypes made these tumor types highly relevant for endoglin targeting." (PMID 33375670, 2020).
cervical cancer (8 papers, 2007 to 2025). A primary or metastatic malignant neoplasm involving the cervix. "ENG expression is elevated during alterations in vascular structure and has been associated to many cancers, including breast, ovary, prostate and cervical cancer." (PMID 23341958, 2013). "Amplification at 9q33-q34 included endoglin, a gene involved in tumor angiogenesis and predictive for metastasis in cervical cancer." (PMID 17311676, 2007). "Endoglin (CD105): CD105 is a TGF-β co-receptor enriched in CAFs from breast, pancreatic, and cervical cancers." (PMID 41441395, 2025). "Recently, other antibodies were used to assess the counts of MVD in cervical cancer, such as CD31 (also known as platelet endothelial cell adhesion molecule), CD34 and CD105 (also known as Endoglin)." (PMID 30305802, 2018). "In this study, we have investigated the role of endoglin (CD105), a regulator of TGF-β signalling on endothelial cells, bFGF and VEGF-A expression in 30 cervical carcinoma specimens." (PMID 19352388, 2009). "In this study, we have investigated the role of endoglin (CD105), a regulator of transforming growth factor (TGF)-β1 signalling on endothelial cells, basic fibroblast growth factor (bFGF) and vascular endothelial growth factor-A (VEGF-A) in cervical cancer." (PMID 19352388, 2009).
diabetic nephropathy (8 papers, 2020 to 2022). "In kidney biopsy obtained from diabetic nephropathy patients, the endoglin level significantly increases compared to the control." (PMID 35281939, 2022). "Although endoglin promotes myofibroblast differentiation in diabetic nephropathy, the role of endoglin in myofibroblasts in the liver still requires further investigation." (PMID 33809908, 2021). "Finally, we previously showed that endoglin is upregulated in myofibroblasts in the interstitium of patients with diabetic nephropathy." (PMID 36614087, 2022). "We first measured renal endoglin expression in biopsy samples obtained from patients with different types of CKD, i.e., IgA nephropathy, focal segmental glomerulosclerosis (FSGS), diabetic nephropathy (DN) and patients with chronic allograft dysfunction (CAD)." (PMID 36614087, 2022). "Moreover, LINC00968, which is co-expressed with ENG and VCAM1, can promote the proliferation and migration of endothelial cells and accelerate the proliferation and fibrosis in diabetic nephropathy." (PMID 33790949, 2021).
epistaxis (8 papers, 2013 to 2025). Bleeding from the nose. "The patient’s HHT symptoms are most likely due to her ENG pathogenic variant, but given her father and half-brother’s clinically significant epistaxis, a synergistic contribution of her GDF2 VUS to her symptoms cannot be excluded completely." (PMID 40429357, 2025). "As previously reported, epistaxis was the most common symptom found in almost all patients with ENG- or ACVRL1-HHT after 12 years of age." (PMID 34872578, 2021). "Epistaxis is the most common (> 90%) manifestation in patients with both ENG and ACVRL1 mutations, although patients with ENG mutations are believed to have onset of epistaxis at a younger age." (PMID 32660636, 2020).
fibrosis (8 papers, 2011 to 2024). the formation of excess fibrous connective tissue in an organ or tissue in a reparative or reactive process. "A strategy focusing on TGF-β pathway genes revealed an enrichment in rare variants of the endoglin gene (ENG) in fibrosis patients." (PMID 31749832, 2019). "The role of endoglin in liver fibrosis and HCC progression also makes it an attractive therapeutic target." (PMID 30563158, 2018). "Furthermore, in patients with advanced HCV-related fibrosis, intrahepatic expression of endoglin was significantly higher than in patients with early fibrosis and normal liver." (PMID 39199400, 2024). "Endoglin is a key protein in liver fibrosis, HCC cell growth, survival, and cancer cell metastasis." (PMID 33809908, 2021). "For ENG, there were seven heterozygous carriers of at least one CCV in the severe fibrosis group and none in the control group." (PMID 31749832, 2019).
angiosarcoma (7 papers, 2016 to 2025). A malignant tumor arising from the endothelial cells of the blood vessels. "The author came across a recent paper, in which the role of Endoglin (CD105) mutations has been studied in angiosarcomas." (PMID 33593408, 2021). "TRC105 is a monoclonal antibody targeting endoglin (CD105) which is expressed by tumor cells in angiosarcomas and up-regulated by VEGF-inhibition." (PMID 31007895, 2019). "Endoglin has been found to act as a coreceptor for TGF-Beta signaling pathway and has been found on malignant endothelial cells of angiosarcoma." (PMID 33593408, 2021). "Anti-angiogenic agents have a substantial role but the failure of a randomized phase 3 trial of pazopanib with or without an anti-endoglin antibody brings a challenge to future trials in angiosarcomas." (PMID 33182685, 2020).
chronic kidney disease (7 papers, 2011 to 2025). Impairment of the renal function secondary to chronic kidney damage persisting for three or more months. "Whether circulating concentrations of soluble endoglin are elevated in CKD or underlie the high risk of cardiovascular death associated with chronic kidney disease (CKD) is unknown." (PMID 21886815, 2011). "Endoglin (ENG), a TGF-β co-receptor involved in the pathogenesis of interstitial fibrosis in chronic kidney disease, has two splicing variants: long-ENG, which undergoes normal splicing, and short-ENG, in which intron 14 is retained." (PMID 40076889, 2025). "Together, these results indicate that endoglin is not only overexpressed in patients with progressive chronic kidney disease but also suggest that overexpression of endoglin in the interstitium contributes to interstitial fibrosis." (PMID 36614087, 2022). "Our finding that endoglin is upregulated in various chronic kidney diseases is in line with current literature." (PMID 36614087, 2022). "It would be interesting to explore if endoglin could be a therapeutic target in chronic kidney disease." (PMID 36614087, 2022). "By using larger cohorts and quantitative image analyses, we were able to demonstrate a significant increase in interstitial endoglin in patients with chronic kidney disease, which was accompanied by higher Sirius Red staining, indicative of increased collagen deposition." (PMID 36614087, 2022). "Future studies are needed to show whether endoglin can serve as a therapeutic target for reducing the formation of renal fibrosis in patients with chronic kidney disease, with the purpose of slowing the renal decline towards ESRD." (PMID 36614087, 2022). "Future studies need to show whether endoglin may serve as a possible therapeutic target for preventing the development of fibrosis in patients with DN, thereby slowing the progression towards end-stage renal disease." (PMID 33081058, 2020). "Endoglin, a 180 KDa membrane glycoprotein, is a TGF-β co-receptor overexpressed in several models of chronic kidney disease, but its function in renal fibrosis remains uncertain." (PMID 25313562, 2014). "Our results suggest that endoglin is an important mediator in the final common pathway of CKD and could be used as a possible new therapeutic target to counteract the progression towards end-stage renal disease (ESRD)." (PMID 36614087, 2022).
clear cell renal cell carcinoma (7 papers, 2016 to 2025). "Interestingly, this trend was also repeated in renal clear cell carcinoma, where INHA was only a predictor of survival in TGFBR3 low (HR = 2.75, p = 9.0E-06) and ENG low (HR = 2.6, p = 2.5E-06)." (PMID 33819300, 2021).
endometriosis (7 papers, 2018 to 2025). The growth of functional endometrial tissue in anatomic sites outside the uterine body. "Among cultured SFCs, we did observe a lower level of expression of CD105 (endoglin) in those isolated from ME collection from endometriosis patients." (PMID 30134794, 2018).